RN7SL499P (RNA, 7SL, cytoplasmic 499, pseudogene)
Gene: Miscellaneous RNA gene on chromosome 2 (231,645,998 to 231,646,273, reverse strand). Ensembl gene ENSG00000239202.
Homologues: Orthologues: chimpanzee Metazoa_SRP (99% identical), macaque Metazoa_SRP (94% identical). Paralogues in human: RN7SL1 (74% identical), RN7SL2 (74% identical), RN7SL650P (74% identical), RN7SL290P (73% identical), RN7SL3 (73% identical), RN7SL91P (72% identical), RN7SL856P (72% identical), RN7SL655P (71% identical), RN7SL125P (71% identical), RN7SL712P (71% identical), RN7SL827P (71% identical), RN7SL220P (70% identical), and 699 more.